MASP2 (MBL associated serine protease 2)
Diseases named in the same sentence as MASP2 in open-access papers (continued):
Sharing a sentence is not in itself a finding about the gene and the disease.
pneumococcal meningitis (5 papers, 2017 to 2023). An acute purulent infection of the meninges and subarachnoid space caused by Streptococcus pneumoniae, most prevalent in children and adults over the age of 60. "Consistent with these human data, Masp2-deficient mice with pneumococcal meningitis had lower cytokine levels and increased survival compared to WT mice." (PMID 28086930, 2017). "In experimental pneumococcal meningitis, Masp2 deficiency led to decreased disease severity through decreased brain inflammation." (PMID 28086930, 2017). "We investigated MASP-2 levels in cerebrospinal fluid (CSF) samples derived from the diagnostic lumbar puncture, which was available for 307 of 792 pneumococcal meningitis episodes (39%)." (PMID 28086930, 2017). "Kasanmoentalib ES, Valls Seron M, Ferwerda B, Tanck MW, Zwinderman AH, Baas F, van der Ende A, Schwaeble WJ, Brouwer MC, van de Beek D. Mannose-binding lectin-associated serine protease 2 (MASP-2) contributes to poor disease outcome in humans and mice with pneumococcal meningitis." (PMID 28385159, 2017). "To investigate the role of MASP-2 in disease progression in pneumococcal meningitis, we infected Masp2−/− (n = 12) and WT (n = 12) mice by intracisternal inoculation with S. pneumoniae serotype 3 (ATCC 6303)." (PMID 28086930, 2017). "MASP-2-specific monoclonal antibodies can be used to attenuate the inflammatory response in pneumococcal meningitis." (PMID 28086930, 2017). "We found that pneumococcal meningitis patients had increased levels of MASP-2 in their CSF compared to controls (median 4.77 vs. 1.19 ng/ml, P < 0.0001)." (PMID 28086930, 2017). "Subsequently, we studied the role of MASP-2 in our experimental pneumococcal meningitis mouse model using Masp2−/− mice and evaluated the potential of adjuvant treatment with MASP-2-specific monoclonal antibodies in wild-type (WT) mice." (PMID 28086930, 2017). "In patients with pneumococcal meningitis, MASP-2 concentration was elevated in the CSF and high levels were associated with poor functional outcome." (PMID 28086930, 2017). "Subsequently, we analyzed the role of MASP-2 during experimental meningitis in our validated pneumococcal meningitis mouse model using Masp2 knockout mice." (PMID 28086930, 2017). "Our study stresses the important role of MASP-2 in pneumococcal meningitis and suggests that MASP-2 inhibitory antibodies can attenuate the harmful inflammatory response during pneumococcal meningitis." (PMID 28086930, 2017). "Our results show that MASP-2 contributes to severity and outcome in pneumococcal meningitis." (PMID 28086930, 2017). "We studied multiple aspects of the role of MASP-2 in pneumococcal meningitis." (PMID 28086930, 2017). "In patients with pneumococcal meningitis, CSF levels of MASP-2 were positively correlated to C5a (ρ = 0.481, P < 0.0001), C5b-9 (ρ = 0.560, P < 0.0001) and the CSF protein concentration (ρ = 0.488, P < 0.0001), but not to CSF leukocyte count (ρ = 0.088, P = 0.130)." (PMID 28086930, 2017). "MASP-2 contributes to poor disease outcome in human and mice with pneumococcal meningitis." (PMID 28086930, 2017). "Deficiency or blockade of MASP-2 in experimental models has been shown to have beneficial effects in ischemic reperfusion injury, transplantation, rheumatoid arthritis, TMA, pneumococcal meningitis, SARS-Cov-2 infection, sickle cell disease, and renal fibrosis." (PMID 38022610, 2023). "Genetic variations in the MASP-2 gene in patients with pneumococcal meningitis did not influence disease severity." (PMID 28086930, 2017). "However, this does not negate the importance of MASP-2 in activation of complement in pneumococcal meningitis." (PMID 28086930, 2017).
Stroke (5 papers, 2010 to 2021). Sudden impairment of blood flow to a part of the brain due to occlusion or rupture of an artery to the brain. "In order to investigate the clinical relevance of these experimental observations, a study of MBL2 and MASP-2 gene polymorphism rendering the lectin pathway dysfunctional was performed in 135 stroke patients." (PMID 20140243, 2010). "Furthermore, in an experimental model of stroke, MASP2-deficient mice showed significantly reduced neurological deficits and histopathological damage after transient ischemia and reperfusion compared to wild-type or control-treated mice." (PMID 33923220, 2021). "We demonstrate that targeting MASP-2 with a specific inhibitory antibody is very effective in limiting both the post-stroke neurological deficits as well as the associated ischemic lesion and in reducing the consequent activation of microglia towards the pro-inflammatory amoeboid phenotype." (PMID 27577570, 2016). "A SNP in the MASP2 gene (D105>G) may also result in low circulating levels of MASP-2 but little is known of its pathogenic consequences after experimental or clinical stroke." (PMID 20140243, 2010). "This work defines the contributions of each of the three LP-associated enzymes—mannan-binding lectin-associated serine protease (MASP)-1, MASP-2, and MASP-3—to ischemic brain injury in experimental mouse models of stroke." (PMID 27577570, 2016). "This study provides a comparative analysis of the phenotypes of mouse lines with targeted deficiencies of the LP-specific serine proteases MASP-1, MASP-2, and MASP-3 in a mouse model of stroke." (PMID 27577570, 2016). "Regarding the MASP2 genotype, post-stroke infections appeared in 2 (13.3%) patients with D105>G SNP and in 22 (18.3%) patients with the wild-type genotype (χ2, p = 0.63)." (PMID 20140243, 2010). "Protection in the MASP-2−/− mice was also observed in an additional model of stroke, the 3VO model." (PMID 27577570, 2016). "Unlike the major contribution of MBL, the study did not unravel a significant involvement of MASP2 genotype or MASP-2 levels in the prognosis of stroke." (PMID 20140243, 2010). "In contrast, the MASP2 genotype did not influence the levels of C3 and C4 after stroke." (PMID 20140243, 2010).
viral infections (5 papers, 2013 to 2024). "We speculate that relative MBL excess in the setting of relatively low C4 levels or deficient MASP-2 may lead to MBL-mediated enhanced viral infections in clinical settings." (PMID 23573288, 2013). "In addition, Il12rb2, F2, and Masp2 are involved in the activities of the cellular immune system and play important roles in viral infections and cancer." (PMID 38225547, 2024). "While the RNASEL gene was shown to play a role during Dengue virus infection, MEFV and MASP2 deficiencies may manifest subclinically, and CFTR deficiency leads to severe outcomes that predominantly involve opportunistic bacterial rather than viral infections." (PMID 39062917, 2024).
acute respiratory distress syndrome (4 papers, 2021 to 2024). Progressive and life-threatening pulmonary distress in the absence of an underlying pulmonary condition, usually following major trauma or surgery. "Inhibition of the lectin pathway activation by a monoclonal antibody targeting MASP-2 has also been shown to reduce acute respiratory distress syndrome (ARDS) severity in mouse models of SARS-CoV-2 infection." (PMID 38911852, 2024).
pneumonia (4 papers, 2020 to 2022). An acute, acute and chronic, or chronic inflammation focally or diffusely affecting the lung parenchyma, caused by an infection in one or both of the lungs (by bacteria, viruses, fungi, or mycoplasma.). "Taken together, these results suggest that suppression of MASP-2-mediated complement overactivation may provide an approach for the treatment of pneumonia in pathogenic coronavirus-infected patients." (PMID 36100602, 2022). "Coronavirus N protein-mediated MASP-2 and thereby complement cascade overactivation can aggravate pneumonia in mice." (PMID 36100602, 2022). "Intriguingly, this interaction not only potentiated MASP‐2‐driven activation of the LP but also aggravated LPS‐induced pneumonia in a MASP‐2‐dependent way." (PMID 32643798, 2021). "In line, MASP-2 knock-out mice and mice treated with MASP-2 inhibitors showed significantly milder symptoms in a virus protein mouse pneumonia model." (PMID 32922409, 2020).
rheumatoid arthritis (4 papers, 2014 to 2023). A chronic, systemic autoimmune disorder characterized by inflammation in the synovial membranes and articular surfaces. "Despite its clinical importance, MASP-2 remains poorly investigated in rheumatoid arthritis (RA)." (PMID 24632598, 2014).
Arthritis (3 papers, 2020). Inflammation of a joint. "Interestingly, studies discussing association of MASP2 and arthritis showed that plasma levels of MASP2 were higher than that in synovial fluid in RA patients, and ratio of synovial fluid/plasma concentration was increased in RA patients compared to OA patients." (PMID 32677764, 2020). "Increased expression of MASP2 was related to clinical, laboratory characteristics including nephritis, arthritis, anti‐dsDNA antibody, cylindruria, hematuria and SLEDAI score." (PMID 32677764, 2020). "It is possible that increased MASP2 in lupus patients may correlate to the development of arthritis, promoting disease severity like the role of MASP2 in arthritis pathogenesis." (PMID 32677764, 2020). "Therefore, for this current study we used GalNAc-MASP-1-siRNA and GalNAc-MASP-2-siRNA duplexes targeting hepatocytes to examine their effect on arthritis." (PMID 32153567, 2020). "However, the clear role of MASP2 contributing to lupus clinical, laboratory features such as arthritis needs discussion in the future." (PMID 32677764, 2020). "The role of MASP-1 and MASP-2 proteases in arthritis has been unknown." (PMID 32153567, 2020). "Patients with arthritis (N = 23) had elevated serum levels of MASP2 when compared with that in patients without arthritis (N = 38) (12 494.59 ± 984.27 vs 12 070.70 ± 583.17 pg/mL, P = .038)." (PMID 32677764, 2020). "However, in there was a decrease (58%) in expression of MASP-3 in the liver from normal mice with arthritis treated with GalNAc-MASP-1-siRNA (data not shown) but not with GalNAc-MASP-2-siRNA (data not shown)." (PMID 32153567, 2020). "When discussed the relationship of serum MASP2 levels and clinical, laboratory features, patients with nephritis, arthritis, anti‐dsDNA antibody, cylindruria, hematuria showed higher expression of MASP2 as compared to that in lupus patients without the characteristics." (PMID 32677764, 2020). "Mice lacking C5 or treated with GalNAc-C5-siRNA or anti-C5 inhibitory antibody do not develop arthritis despite the presence of MASP-1 and MASP-2." (PMID 32153567, 2020). "We evaluated the effects of N-acetylgalactosamine (GalNAc)-conjugated MASP-1 and MASP-2 duplexes in vitro and in mice with and without arthritis to examine whether knockdown of MASP-1 and MASP-2 expression affects the development of arthritis." (PMID 32153567, 2020).
Autoimmunity (3 papers, 2013 to 2021). The occurrence of an immune reaction against the organism's own cells or tissues. "A known mutation in human MASP2 was associated with susceptibility to severe infections and autoimmunity." (PMID 23934554, 2013). "While MASP-2 and lectin pathway components are highly conserved in immune defenses, loss of MASP-2 regulates infectious or autoimmune diseases, immunodeficiency of which are significantly associated with pyogenic bacterial infections, inflammatory lung disease, and autoimmunity." (PMID 33718121, 2020).
glaucoma (3 papers, 2019 to 2021). Increased pressure in the eyeball due to obstruction of the outflow of aqueous humor. "This correlates with up-regulated levels of C1, C8, and C9, as well as MASP1 and MASP2 in retinal tissues from glaucoma donor eyes." (PMID 34943212, 2021). "In glaucoma human donor eyes, proteomic analysis revealed an upregulation of proteins linked to the lectin pathway, such as MASP1 and MASP2." (PMID 31543759, 2019). "In addition, increased levels of several complement components, including MASP2 were found in glaucoma patients." (PMID 34867198, 2021).
Hepatitis (3 papers, 2018 to 2026). Inflammation of the liver. "The serum MASP-2 levels in patients with severe histological hepatitis were significantly lower than those in patients with mild histological hepatitis." (PMID 35677590, 2022).
Immunodeficiency (3 papers, 2020 to 2023). Failure of the immune system to protect the body adequately from infection, due to the absence or insufficiency of some component process or substance. "The MBL collagen regions form complexes with the serine proteases MASP-1 and MASP-2 in order to activate complement, and mutations lead to common immunodeficiencies." (PMID 36528062, 2023).
ischemia (3 papers, 2014 to 2025). A hypoperfusion of the BLOOD through an organ or tissue caused by a PATHOLOGIC CONSTRICTION or obstruction of its BLOOD VESSELS, or an absence of BLOOD CIRCULATION. "Reduced MASP-2 levels due to protein consumption were also recently associated with ischemia-related necrotic myocardial injury in a human cohort." (PMID 24632598, 2014). "This notion finds support in preclinical evidence showing abnormal L-fucose expression on tubule cells in kidneys exposed to ischemia, inducing autonomous binding to collectin-11, and activating the lectin pathway via MASP-2 interaction following reperfusion." (PMID 38106604, 2023).
lupus (3 papers, 2018 to 2020). "To further reveal the association of MASP2 gene polymorphisms with lupus clinical, laboratory features, we did subgroup analysis." (PMID 32677764, 2020). "To discuss the possible role of MASP2 gene polymorphisms on serum levels of MASP2 in lupus patients, we analysed the correlation between polymorphisms and serum levels of MASP2." (PMID 32677764, 2020). "In the present study, a total of 250 lupus patients and 385 age, sex‐matched healthy volunteers were selected to discuss the MASP2 gene polymorphisms (rs7548659, rs17409276, rs2273346, rs1782455 and rs6695096) and disease susceptibility." (PMID 32677764, 2020). "Compared with previous findings, there is limited evidence about MASP2 in autoimmune diseases especially association with lupus." (PMID 32677764, 2020). "The association of LP serine proteases MASPs (MASP-1, MASP-2, and MASP-3) and MBL-associated proteins MAps (MAp19 and MAp44) with lupus characteristics has also previously been assessed." (PMID 29892304, 2018). "Therefore, discussing MASP2 gene polymorphism is of importance to reveal the lupus genetic susceptibility." (PMID 32677764, 2020). "Therefore, we analysed the association of different gene polymorphisms and MASP2 protein expression in lupus patients from the training cohort." (PMID 32677764, 2020). "In this study, we recruited 250 lupus patients and matched with 385 sex, age comparable healthy volunteers to discuss the MASP2 rs7548659, rs17409276, rs2273346, rs1782455 and rs6695096 polymorphisms." (PMID 32677764, 2020). "Results showed that lupus patients showed significantly up‐regulated serum levels of MASP2 when compared to that in different rheumatic patients (All P < .001)." (PMID 32677764, 2020). "This study is the first time to report serum levels of MASP2 in lupus patients with large sample size." (PMID 32677764, 2020). "In training cohort, there were 61 lupus patients and 98 age, sex‐matched healthy controls, and serum levels of MASP2 were significantly higher in lupus patients as compared to that in controls (12 230.52 ± 779.65 vs 7174.45 ± 999.45 pg/mL, P < .001)." (PMID 32677764, 2020). "ROC analysis indicated that area under curve (AUC) was 0.999 when serum levels of MASP2 in lupus patients compared to that in RA patients." (PMID 32677764, 2020). "We firstly compared serum levels of MASP2 in lupus patients and healthy controls by the training cohort and found that there was elevated expression of MASP2 in SLE." (PMID 32677764, 2020). "To further confirm the potential of serum MASP2 as a biomarker of lupus, we conducted a validation cohort that included 100 SLE patients, 100 RA patients, 100 OA patients, 100 gout patients, 44 SS patients and 41 AS patients." (PMID 32677764, 2020). "The findings suggested that MASP2 may be a potential disease marker for lupus, and correlate with SLE pathogenesis." (PMID 32677764, 2020). "Therefore, in the present study, we discussed serum levels of MASP2 in lupus patients with large samples and revealed the SLE genetic susceptibility with MASP2 single nucleotide polymorphism (SNP)." (PMID 32677764, 2020). "Fourth, different reagents to detect the protein expression of MASP2 in lupus patient may have different results." (PMID 32677764, 2020). "Results showed that serum levels of MASP2 were significantly higher in lupus patients and correlated with some clinical, laboratory characteristics in the training cohort, and were much higher as compared to that in different rheumatic diseases patients in the validation cohort." (PMID 32677764, 2020). "However, lupus patients carrying genotypes GG, GA, AA for rs17409276, TT, CT, CC for rs6695096 had significantly different serum levels of MASP2, by which carrying GA genotype for rs17409276, carrying TT, TC genotype revealed higher expression of MASP2." (PMID 32677764, 2020).
lupus (continued). "Similarly, serum MASP2 in lupus patients compared with that in gout, OA, SS and AS patients revealed AUC of 0.999, 0.962, 0.982, 0.993, respectively." (PMID 32677764, 2020). "As the serum levels of MASP2 were higher in SLE patients and related to several clinical, laboratory characteristics as shown in the training cohort, it is possible that dysregulated serum MASP2 may be a disease marker for lupus." (PMID 32677764, 2020). "The other clinical, laboratory characteristics were not related to MASP2 expression in lupus patients (data not shown)." (PMID 32677764, 2020). "As dysregulation of the complement system has been demonstrated to correlate with SLE pathogenesis, the role of MASP2 in lupus has not been widely discussed." (PMID 32677764, 2020). "Lupus patients with cylindruria (N = 5) also had elevated serum levels of MASP2 than that in patients without the parameter (N = 56) (13 414.07 ± 1472.66 vs 12 124.85 ± 605.53 pg/mL, P < .001)." (PMID 32677764, 2020). "Only a study with 58 female lupus patients showed that plasma levels of MASP2 were not significantly different from that in healthy controls." (PMID 32677764, 2020). "Similarly, lupus patients with positive anti‐dsDNA (N = 15) revealed increased expression of MASP2 in serum than that in patients with negative anti‐dsDNA antibody (N = 46) (12 825.41 ± 1074.12 vs 12 036.54 ± 543pg/mL, P < .001)." (PMID 32677764, 2020). "Interestingly, plasma concentrations in lupus patients were higher than the healthy controls regarding MASP-1, MASP-3, and MAp44, but not MASP-2." (PMID 29892304, 2018).
lymphoma (3 papers, 2018 to 2021). A malignant (clonal) proliferation of B- lymphocytes or T- lymphocytes which involves the lymph nodes, bone marrow and/or extranodal sites. "Heterozygosity for MASP2 gene +359 A>G mutation was relatively frequent in lymphoma patients who experienced bacteremia during hospital stay." (PMID 30294330, 2018). "The results of a retrospective study indicated that higher MASP-2 serum concentrations are associated with a longer event-free survival (EFS) in children with lymphoma (especially HL)." (PMID 30294330, 2018). "Both papers documented possible associations of factors specific for the lectin pathway of complement (especially on genetic background) with multiple myeloma or lymphoma (MBL, ficolin-1, ficolin-2) or hospital infections (MASP-2, ficolin-3)." (PMID 32047495, 2019).